ENSG00000251828
Synonyms: LOC124900204
Gene: Small nucleolar RNA gene on chromosome 5 (80,306,235 to 80,306,368, reverse strand). Ensembl gene ENSG00000251828.
Gene Ontology:
Biological process: RNA processing
Cellular component: nucleolus
Homologues: Paralogues in human: SNORA31B (79% identical), SNORA31 (66% identical).